MYH9 (myosin heavy chain 9)
Diseases named in the same sentence as MYH9 in open-access papers (continued):
Sharing a sentence is not in itself a finding about the gene and the disease.
renal failure (11 papers, 2013 to 2025). "As a motor protein, abnormal MYH9 expression, localization, or function change will lead to cytoskeleton damage, further causing proteinuria or renal failure in patients with CKD." (PMID 29862302, 2018). "MYH9-RD are rarely life-threatening unless they cause renal failure." (PMID 32545517, 2020). "However, it remains unclear how certain non-coding MYH9 variants exert their epistatic role and are associated with renal failure." (PMID 23516419, 2013). "Approximately one-third of patients with MYH9-related disorder have kidney dysfunction characterized by progressive proteinuria, glomerulosclerosis with foot process effacement, and kidney failure." (PMID 33001861, 2020). "MYH9-RD patients may benefit from regular urine analysis, since appearance of proteinuria may support the use of therapies such as angiotensin II receptor blockers (ARB-II) and/or angiotensin-converting enzyme inhibitors (ACEI), aiming to prevent or delay kidney failure." (PMID 33926054, 2021).
Bernard-Soulier syndrome (10 papers, 2011 to 2025). Bernard Soulier syndrome (BSS) is an inherited platelet disorder characterized by mild to severe bleeding tendency, macrothrombocytopenia and absent ristocetin-induced platelet agglutination. "In addition, MYH9 mutation is related to FSGS in the giant platelet syndromes, a clinical fact that suggests that this protein actually has a role in the podocyte biology." (PMID 24658608, 2014). "However, very little is known about the mechanisms by which MYH9 mutations cause kidney disease in vivo in rare Giant Platelet syndromes and possibly in more common forms of kidney disease." (PMID 23874454, 2013). "Of the 20 confirmed diagnoses, one case in the IPND Group had a MYH9 macrothrombocytopenia confirmed by a genetic panel, and 19 in the IPFD Group had Glanzmann thrombasthenia (13 cases), Bernard-Soulier syndrome (five cases) and storage pool disease (one case) confirmed by electron microscopy." (PMID 40300270, 2025).
diabetes (10 papers, 2011 to 2023). "Despite the lack of previous association with diabetic-ESRD, two subsequent studies found significant association of MYH9 with type 2 diabetes mellitus (T2DM)-ESRD." (PMID 30359254, 2018). "We investigated the association of MYH9 SNPs with renal traits in a mixed-ancestry South African population prone to diabetes." (PMID 23285077, 2012). "Later the authors showed MYH9 polymorphisms specifically the E-1 haplotype to modulate the genetic effect of FERM domain-containing protein 3 (FRMD3) for diabetes susceptibility." (PMID 23285077, 2012). "Taken together with the diabetes-renal disease risk, it is likely that MYH9 exerts this effect through disregulation of blood glucose metabolism, as such future work is warranted." (PMID 23285077, 2012). "Type 2 diabetes remains the strongest risk factor for renal diseases, but MYH9 polymorphisms are only weakly associated with diabetes related ESRD in both African and European Americans." (PMID 23285077, 2012). "Further information on APOL1/MYH9 variants may lead to screening programs which could lead to earlier detection and interventions for non-diabetic kidney disease." (PMID 22956460, 2013). "The role of MYH9 in diabetes susceptibility has previously been proposed." (PMID 23285077, 2012). "Thus, our aim was to explore the association between MYH9 SNPs and renal traits in the mixed ancestry population of South Africa which has previously been shown to have a high prevalence of diabetes." (PMID 23285077, 2012). "Moreover, genetic variability in the gene locus has also been shown to alter podocyte structure, making these cells more injury-prone after a damaging stimulus, and MYH9 SNPs have been shown to be associated with ESRD linked to diabetes in Europeans and African Americans." (PMID 34946941, 2021). "MYH9, ERBB2, TCF4, VIM (vimentin), LRRK2 and CAV1 have been implicated as a principal mediator of diabetes mellitus." (PMID 36837510, 2023). "The collective data also indicate that MYH9 function is disrupted in diabetic mellitus, which may contribute to the pathogenesis of diabetic kidney injury." (PMID 31118506, 2019). "Similarly, genome-wide linkage analysis has revealed genetic variants on chromosome 22, near the MYH9 and APOL1 to be linked to the pathogenesis of diabetes." (PMID 23285077, 2012). "MYH9 rs3752462 (T>C) and APOL1 rs136161 (C>G) were genotyped in 303 DKD patients and 364 type 2 diabetes mellitus (T2DM) patients without kidney disease using the TaqMan SNP genotyping assay." (PMID 29862302, 2018).
glomerular disease (10 papers, 2009 to 2024). "Podocyte­specific deletion of Myh9 in C57BL/6 mice causes significant susceptibility to experimental doxorubicin hydrochloride glomerulopathy." (PMID 29862302, 2018). "As previously discussed, Myh9 and Actn4 encode proteins that are predominately expressed in the podocyte within the glomerulus and have been associated with genetic forms of glomerular disease." (PMID 19652713, 2009). "However, the mechanisms underlying MYH9-related glomerular diseases associated with proteinuria are poorly understood." (PMID 31118506, 2019). "Loss of expression of Myh9 in podocytes predisposed mice to adriamycin-induced glomerulopathy." (PMID 24949636, 2014). "Mutations in the genes that code for proteins that are expressed in podocytes including nephrin, podocin, WT1, α-actinin-4, inverted formin 2 (INF2), TrpC6, MYH9, and phospholipase Cε1, lead to glomerular disease." (PMID 27942003, 2016). "Importantly, the genes that encode several of these mRNAs (e.g. Actn4, Myh9) have previously been implicated in genetic forms of kidney disease or the encoded proteins have been shown to interact with gene products that have been shown to play a role in glomerular disease." (PMID 19652713, 2009). "The role that common SNPs in MYH9 play in glomerular diseases is less clear." (PMID 24949636, 2014). "We previously hypothesized that disruption of MYH9 function results in glomerular disease due to podocyte dysfunction." (PMID 23874454, 2013). "However, genome-wide analyses have found associations between MYH9 SNPs and glomerular disease independent of APOL1." (PMID 24949636, 2014).
glomerulosclerosis (10 papers, 2012 to 2023). A hardening of the kidney glomerulus caused by scarring of the blood vessels. "As described in the Introduction, mutations in human MYH9 cause a rare, autosomal dominant Giant Platelet syndrome with variably expressive but severe glomerulosclerosis that progresses to end stage kidney disease in young adults." (PMID 23874454, 2013). "One-third of patients with dominant MYH9-mutations, those previously classified as having Epstein's or Fetchner's Syndrome, develop glomerulosclerosis and progress to end stage kidney disease requiring dialysis or transplantation by the 2nd or 3rd decade." (PMID 23874454, 2013). "We previously reported that podocyte-specific deletion of Myh9 (conventional myosin heavy chain 2A) in C57BL/6 mice does not cause spontaneous kidney disease but instead results in a predisposition to glomerulosclerosis in response to a second model of glomerular injury." (PMID 23874454, 2013). "The second question addressed in this study was whether podocyte-specific deletion of Myh9 on the C57BL/6 background results in predisposition to glomerulosclerosis in general, perhaps from a “weakened” podocyte, or whether the predisposition is specific to Adriamycin injury." (PMID 23874454, 2013). "In contrast, other investigators reported that podocyte-specific deletion of Myh9 (PodΔMyh9) resulted in spontaneous glomerulosclerosis in mice on a mixed background, suggesting that the glomerulosclerosis is dependent on background strain." (PMID 23874454, 2013). "Based on these and other data, APOL1 supplanted MYH9 as the candidate disease gene for glomerulosclerosis and hypertensive nephrosclerosis among African-Americans." (PMID 23300552, 2012). "Both groups found that African-American glomerulosclerosis correlates more strongly with the G1 and G2 alleles of APOL1, which lies immediately centromeric to MYH9." (PMID 23300552, 2012). "In contrast to MYH9, APOL1 can explain why the alleles proposed to cause glomerulosclerosis are found at such high frequency in the African-American population." (PMID 23300552, 2012). "According to this hypothesis keloids formation and glomerular sclerosis share similarities of pathogenesis and histology, with the presumed MYH9 variation involvement." (PMID 32873246, 2020). "In previous work we reported that a podocyte-specific deletion of Myh9 in mice (PodΔMyh9) on the C57BL/6 strain background had no overt phenotype but instead resulted in a predisposition to glomerulosclerosis in response to a second injury from Adriamycin." (PMID 23874454, 2013). "In human patients with autosomal dominant MYH9-disease some families with the identical mutation and similar platelet phenotypes have an all-or-nothing kidney disease, suggesting that additional gene-gene or gene-environment interactions are involved in MYH9-dependent glomerulosclerosis." (PMID 23874454, 2013). "While glomerulosclerosis arises more often in patients with missense mutations that affect the N-terminal motor domain of MYH9 rather than the tail domain, patients with the same amino acid change can develop any of the four previously distinct syndromes." (PMID 23874454, 2013). "In our previous work, based on the phenotype of glomerulosclerosis in patients with both Epstein's or Fetchner's syndrome and the association of risk polymorphisms in MYH9 with idiopathic and HIV-related glomerulosclerosis, we hypothesized that a predominant site of action should be the podocyte." (PMID 23874454, 2013). "Why MYH9 intronic polymorphisms would be associated with some but not all common kidney diseases remains unclear, as does the underlying mechanism by which MYH9 autosomal dominant mutations result in glomerulosclerosis." (PMID 23874454, 2013). "The mechanism for the apparent all-or-nothing phenotype of glomerulosclerosis from patients with the same dominantly inherited amino acid change in MYH9 is not understood." (PMID 23874454, 2013).
glomerulosclerosis (continued). "In addition, based on the lack of a spontaneous phenotype of glomerulosclerosis in both C57BL/6 and FVB/N mice, we propose that Myh9 is not absolutely required in adult podocytes." (PMID 23874454, 2013).
lung carcinoma (10 papers, 2013 to 2025). "The overexpression of MYH9 has been found in many cancers, including colorectal, gastric, esophageal, nasopharyngeal, and lung cancers; this upregulation is associated with poor prognosis." (PMID 36139430, 2022). "MYH9 expression in the cell membrane, cytoplasm, and nucleus and survival prognosis of patients with lung cancer were 0.0066, 0.0350 and 0.0368, respectively, which further confirmed that MYH9 was closely related to the prognosis of patients with NSCLC." (PMID 34635641, 2021). "The expression of MYH9 was positively correlated with the survival and prognosis of patients with lung cancer and can be used as an independent index, providing a new potential target for treating patients with lung cancer." (PMID 34635641, 2021). "Furthermore, in HCC and lung cancer, cinobufotalin exerts an anti-tumor action by decreasing the levels of MYH9." (PMID 39273383, 2024). "Recent reports have shown that Myh9 is crucial for maintaining stemness of lung cancer cells and promoting tumorigenesis via activating mTOR signals, suggesting Myh9 may exert a profound function on stem cells." (PMID 35740994, 2022). "Also, we used an immunohistochemical (IHC) assay to analyze the expression of MYH9 in clinical tissue samples of lung cancer and found that it can be used as an independent factor in evaluating the prognosis of patients with NSCLC." (PMID 34635641, 2021). "Also, IHC was performed to verify the role of MYH9 in the growth, invasion, and stemness of lung cancer xenografts." (PMID 34635641, 2021). "Importantly, high expression of MYH9 in lung cancer is positively correlated with poor clinical prognosis and is an independent risk factor for patients with NSCLC." (PMID 34635641, 2021). "Further, through thousands of protein screenings, we identified four proteins (MYH9, GNB1, ALOX12B, HSD17B4) that can predict the response to MET inhibitors for MET-dysregulated lung cancer patients." (PMID 36612298, 2023). "As an example, myosin heavy chain 9 (MYH9) and Copine III (CPNE3) positively correlate with the migration and invasion properties of lung cancer cell lines." (PMID 27018053, 2016). "Non-muscle myosin heavy chain 9 (MYH9) can promote the progression of various tumors, but its effect on the stem cell-like characteristics of lung cancer cells (LCCs) has not been clarified." (PMID 34635641, 2021).
melanoma (10 papers, 2020 to 2024). A malignant, usually aggressive tumor composed of atypical, neoplastic melanocytes. "Collectively, these observations support a model that ectopic expression of WT-Bmal1 or dHLH-Bmal1 sequesters Myh9, modulates SRF activity, and promotes an immune resistant mesenchymal melanoma cell state associated with increased AP-1 enhancer activity." (PMID 38245503, 2024). "Collectively, the evidence supports an interaction between Bmal1 proteins and Myh9 in mouse and human melanoma cell lines." (PMID 38245503, 2024). "MYH9 knockdown or silencing in melanoma cells promoted tumor growth and metastasis." (PMID 39273383, 2024). "Our work describes a link between Bmal1, Myh9, mouse melanoma cell plasticity, and tumor immunity." (PMID 38245503, 2024). "An additional study found that genetically knocking down MYH9 in mouse melanoma cells increased growth and metastasis in vivo in mouse models which was attributed to increased epithelial to mesenchymal (EMT) markers and potentially increased angiogenesis and inflammatory cell recruitment." (PMID 37200287, 2023). "RAC1 is found to be mutually exclusive with MYH9, a tumor suppressor in melanoma." (PMID 34899838, 2021). "MYH9 has also been shown to contribute to a secretory phenotype that reshaped the local environment and vasculature to support growth of melanoma cells 42, and is required for T lymphocyte migration 43, maturation of the immunological synapse 43 and the cytotoxicity of natural killer cells." (PMID 32685004, 2020). "Moreover, MYH9 suppression accelerates tumor growth and metastasis in mouse models of melanoma." (PMID 39149512, 2024). "Collectively, our findings indicate that knockdown of Myh9 phenocopies ectopic expression of Bmal1 proteins in YUMM2.1 cells and confers an immune resistant mesenchymal melanoma cell state." (PMID 38245503, 2024). "Therefore, in a melanoma mouse model, MYH9 may act as a potential tumor suppressor." (PMID 39273383, 2024). "Among the Bmal1 interactors, we chose to focus on Myh9 (non-muscle myosin IIA) in depth, because it has been implicated in melanoma tumorigenesis and drug resistance, and thought to be a tumor suppressor in several tumor models." (PMID 38245503, 2024). "Altogether, however, biological insights from the sequencing and proteomic data are corroborated by functional luciferase reporter assays and tumorigenesis studies, supporting the connections between Bmal1, Myh9, MRTF/SRF, AP-1, melanoma cell states and immune evasion." (PMID 38245503, 2024). "Additionally, MYH9 influences the tumor microenvironment (TME) by modulating leukocyte and macrophage infiltration in tumors, which suggests an unexpected role as a melanoma tumor suppressor." (PMID 39149512, 2024).
non-small cell lung carcinoma (10 papers, 2015 to 2025). A group of at least three distinct histological types of lung cancer, including non-small cell squamous cell carcinoma, adenocarcinoma, and large cell carcinoma. "In non-small cell lung cancer, MYH9 activates the mTOR signaling pathway, enhancing stemness features." (PMID 39988672, 2025). "The miR-138-5p/MYH9 axis boosted cisplatin resistance and decreased immune response in cancer cells in non-small cell lung cancer (NSCLC)." (PMID 39149512, 2024). "A study on non-small cell lung cancer indicated MYH9 expression in both cytoplasm and cell membrane of about 38% of cases." (PMID 34425650, 2021).
Hypertension (9 papers, 2010 to 2025). The presence of chronic increased pressure in the systemic arterial system. "In the development of hypertension and atherosclerosis, inhibiting the formation of F‐actin and promoting the degradation of MYH9 protein can reverse vascular remodelling." (PMID 40070032, 2025). "The nonmuscle myosin heavy chain 9 (MYH9) is strongly associated with hypertension-associated ESRD in African Americans." (PMID 38345042, 2024). "Nonmuscle myosin IIA (MYH9) has been reported to be associated with the increased susceptibility to hypertension and related CKD progression to ESRD in African Americans and a Chinese population." (PMID 33377622, 2021). "More than 50 genetic variants have been identified that are potentially associated with the decline of kidney function and the development of hypertension and renal injury in various studies, among which the most frequently identified gene variants are UMOD, MYH9, APOL1, SHROOM3, RAB38, and DAB2." (PMID 33377622, 2021).
prostate carcinoma (9 papers, 2017 to 2026). A carcinoma that arises from epithelial cells of the prostate gland. "Specifically, OTUD4 inhibits MYH9 degradation via deubiquitination, thereby enabling MYH9-mediated suppression of prostate cancer." (PMID 41930143, 2026). "Experimental evidence suggests that MYH9 acts as a novel androgen receptor co-repressor, playing a pivotal role in the progression of treatment-resistant prostate cancer." (PMID 39149512, 2024). "Cell growth was slower for MYH9 KD cells compared to scramble control cells, suggesting an oncogenic role of MYH9 in prostate cancer cells." (PMID 35589707, 2022). "Our bioinformatics analysis from TCGA dataset showed, for prostate cancer tissues, a positive correlation of mRNA expression of MYH9 with mRNA expression of GSK3β, β-catenin, cyclin D1, c-MYC, vimentin, and N-cadherin." (PMID 35589707, 2022). "Conversely, MYH9 was found to be downregulated in the extracapsule of aggressive prostate cancers versus organ-confined disease phenotypes." (PMID 33959503, 2021). "The RNA expression of caveolin-1 and myosin heavy chain-9 were significantly downregulated in African-American prostate cancer specimens compared to Caucasian-American prostate cancer specimens (p < 0.01 and p < 0.05, respectively)." (PMID 28697756, 2017). "Thus, the functional consequence of TUBB4A/MYH9 interaction in prostate cancer cells may be through two potential mechanisms." (PMID 35589707, 2022). "MYH9 interacts with TUBB4A to safeguard the nucleus during cell migration, promoting the progression of prostate cancer via GSK 3β/β-catenin signaling." (PMID 39149512, 2024). "Human tubulin beta class IVa (TUBB4A) interacts with MYH9 to protect against nuclear DNA damage and promotes cell EMT and migration via activation of GSK3β/β-catenin signalling in prostate cancer." (PMID 37875476, 2023). "In the present study of prostate cancer cells, TUBB4A directly interacted with MYH9 and reduced GSK3β ubiquitination and degradation." (PMID 35589707, 2022). "To determine the role of endogenous MYH9 in growth of prostate cancer cells, we performed proliferation assays for DU145, PC3, and LNCaP scrambled and MYH9 KD cells." (PMID 35589707, 2022). "In summary, in prostate cancer cells, TUBB4A facilitates tumor growth and metastasis through MYH9-mediated GSK3β/β-catenin signaling." (PMID 35589707, 2022). "Although MYH9 has been previously reported to act as a tumor suppressor in prostate cancer, no experimental evidence had demonstrated that MYH9 inhibits prostate cancer growth." (PMID 41930143, 2026).